CRP (C-reactive protein)
Diseases named in the same sentence as CRP in open-access papers (continued):
Sharing a sentence is not in itself a finding about the gene and the disease.
cancer (continued). "However, in cancer patients, interpreting these biomarkers can be challenging due to the underlying malignancy and treatment-related factors that can also elevate CRP and PCT levels." (PMID 41303127, 2025). "Additionally, univariate and multivariate Cox regression analyses revealed that inflammatory subtype (p = 0.042), cancer stage (p = 0.008), and abnormal CRP (C‐reactive protein) level (p = 0.036) were risk factors affecting prognosis." (PMID 40667651, 2025). "CRP is an important downstream inflammatory marker that is known to exhibit both pro-inflammatory and anti-inflammatory functions and is associated with different diseases including cardiovascular disease and cancer." (PMID 40859402, 2025). "In addition to CRP, renal function, measured via eGFR, was investigated for its potential role in modulating cancer risk, given its known association with systemic inflammation." (PMID 40076898, 2025). "Additionally, higher CRP levels were associated with the prediction of 12 cancer types, according to the results of a cohort study; meanwhile, in another cohort, higher CRP levels were found among the frail group (compared to healthy and in-between groups)." (PMID 40565981, 2025). "While inflammation has been implicated in both cancer and AF, the association between C-reactive protein (CRP) and AF risk in CSs remains unclear." (PMID 41387931, 2025). "However, only blood cell counts and CRP partly mediated the associations of AID genetic predisposition with cancer, while overlapping susceptibility between the two diseases or the use of immunosuppressant drugs were generally not found as potential mediators." (PMID 40386413, 2025). "Therefore, CRP levels in this study are believed to reflect chronic inflammation associated with cancer, which further supports its role as an independent prognostic factor." (PMID 41181583, 2025). "For instance, the use of immunosuppressant mediated 16.59% of the association between AIDs at baseline and overall cancer risk, and 56.20% mediated by 8 peripheral biomarkers (e.g., basophil, CRP, high light scatter reticulocyte, monocyte, neutrophil, platelet, RBC width, WBC)." (PMID 40386413, 2025). "Taken together, these data suggest that famine-induced epigenetic re-programming could constitute a durable biological memory that links our cohort’s elevated CRP and heightened cancer risk." (PMID 40936900, 2025). "For example, increased C-reactive protein (CRP) levels are known to indicate systemic inflammation and are associated with a higher risk of cancer, greater tumor aggressiveness, and unfavorable prognosis in various cancers, including those secondary to radiation exposure." (PMID 40282466, 2025). "Elevated CRP has been associated with poor prognosis following cancer surgery." (PMID 40731923, 2025). "Second, although we preliminarily observed that CRP levels may be related to cancer prognosis, different types of cancer are associated with varying degrees of inflammatory response." (PMID 40771356, 2025). "Additionally, serum C-reactive protein significantly mediated 5.3%–20.4 %, 4.5%–18.1 %, and 3.3%–15.7 % of the associations of vitamin C, 25(OH)D, β-carotene, and lycopene with all-cause, cancer, and cardiovascular mortality, respectively." (PMID 40023976, 2025). "Furthermore, high levels of CRP in the blood are associated with the progression of cancer to advanced stages and poor prognosis." (PMID 40141426, 2025). "Therefore, CRP being a sensitive marker for inflammation and tissue damage can be used both as diagnostic and prognostic markers for cancers." (PMID 41367907, 2025). "Taking into consideration that high levels CRP were found to be strongly associated with cancer severity, salivary IL-6 and CRP, along with miR-320a, could be used as indicators for healthy mucosa transition to OLP and, further, to OSCC." (PMID 41303164, 2025).
cancer (continued). "Moreover, the analysis of follow-up CRP values during neoadjuvant treatment would be of interest to detect potential CRP flares, as early dynamic CRP changes have been associated with favorable treatment response in other cancers." (PMID 40102864, 2025). "CRP, a marker for inflammation, can interact with inflammatory and stromal cells in the tumor microenvironment, reflecting tumor cell proliferation, metastasis and overall cancer risk and prognosis." (PMID 39367492, 2024). "In the sensitivity analysis, after excluding patients who experienced an event in the first year, were using medications, had a family history of cancer, had high-fat diet pattern or had acute inflammation (CRP>10 mg/L), the increased cancer risk in the G3 to G6 groups remained." (PMID 38386717, 2024). "In addition, for each standard deviation increase in CRP, the risks of all-cause and cancer mortality increased by 25.9% and 35.4%, respectively (P < 0.05)." (PMID 38858782, 2024). "Therefore, this cross-sectional study aims to assess the association between serum CRP levels and COVID-19 pneumonia in cancer patients infected with the Omicron variants from December 8, 2022 to February 1, 2023 in China." (PMID 38215120, 2024). "Notably, the pre-dialysis MIS was positively associated with the baseline MIS, age, eGFR, cardiovascular disease, and cancer but negatively associated with CRP log and phosphorus level." (PMID 39683409, 2024). "Moreover, pro-inflammatory cytokines including pro-adrenomedullin, pro-endothelin, and the acute phase C-reactive Protein (CRP) were also associated with an increased risk of cancer." (PMID 39340596, 2024). "Therefore, when screening high-risk populations of cancer survivors, we should specifically focus on individuals with simultaneous increases in CRP levels and decreases in albumin levels." (PMID 39358685, 2024). "However, in our findings, elevated levels of C-reactive protein were attributed to a systematic inflammatory state associated with poor nutritional status in cancer patients." (PMID 38723006, 2024). "Research has indicated that patients with malignant tumors suffer various degrees of CRP elevation.The process by which CRP rises in cancer patients is associated with the growth and division of tumor cells, which in turn triggers the activation of inflammatory cells and associated components." (PMID 38384810, 2024). "Thirdly, the sample size in this study was relatively limited, and a larger sample might unveil associations between serum CRP levels and severe COVID-19 pneumonia in cancer patients." (PMID 38215120, 2024). "Furthermore, high CRP levels were associated with specific tumour immune traits including an augmented macrophage response and were significantly linked to poorer cancer-specific survival, particularly in patients with microsatellite-stable tumours." (PMID 39613865, 2024). "Additionally, the assessment of C-reactive protein allowed us to evaluate systemic inflammation, which has been linked to cancer progression." (PMID 38181425, 2024). "Similarly, our study showed that higher CRP/Albumin ratio was independently associated with higher cancer related mortality." (PMID 38803531, 2024). "Generally, inflammatory markers, such as NLR, PLR, LMR, and CRP, were reported their associations with cancer cachexia, and some previous reports demonstrated that the elevations of these inflammatory markers were associated with poor outcome of cancer patients treated with ICIs therapy." (PMID 38775896, 2024). "Elevated CRP levels can indicate cancer risk and progression." (PMID 39498386, 2024). "The carcinogenesis process initiates systemic inflammation, the seventh hallmark of cancer, with a resultant increase in proinflammatory cytokines that stimulate the increased hepatic synthesis of C-reactive protein (CRP), a widely researched measure of inflammation." (PMID 38975012, 2024).
cancer (continued). "Furthermore, the “b” allele is correlated to a high CRP value even in cachectic cancer patients, a clinical characteristic that exposes these individuals to increased mortality." (PMID 38397922, 2024). "Therefore, chest CT images are recommended when cancer patients with Omicron variant COVID- 19 diseases have high CRP levels." (PMID 38215120, 2024). "Abnormal blood test results associated with cancer included low albumin (positive likelihood ratio 3.24, 3.13 to 3.35) and raised platelets (3.48, 3.35 to 3.62), total white cell count (3.01, 2.89 to 3.14), and C reactive protein (3.13, 3.05 to 3.20)." (PMID 39414353, 2024). "CRP showed the strongest association, indicating that inflammatory processes might mediate the effects of cancer in HF." (PMID 39340596, 2024). "Patients with cancer and elevated CRP levels had an 80% greater risk of early death." (PMID 39001318, 2024). "Common tests like C-reactive protein (CRP), raised neutrophils, and raised platelets may be useful to identify people at risk of cancer." (PMID 39054298, 2024). "Elevated CRP levels are associated with poor prognosis in various types of cancer." (PMID 38913646, 2024). "Notably, increased levels of circulating inflammatory markers, such as C-reactive protein (CRP), are associated with an elevated risk of cancer in the breast, ovaries, colon, lungs, and prostate." (PMID 38279253, 2024). "Several biomarkers related to inflammation, such as the NLR, GPS, lymphocyte-CRP ratio, systemic inflammation response index, and CRP-albumin ratio, have been reported to be associated with prognosis in patients with a variety of cancers, including STS." (PMID 38473433, 2024). "Similarly, the cancer mortality risk for individuals in the highest tertile of CRP levels increased by 283.9%." (PMID 38858782, 2024). "However, it has been shown that elevated baseline CRP is associated with poor response to chemotherapy and adverse disease outcomes in cancer patients, including advanced NSCLC." (PMID 39590174, 2024). "It is still unknown, though, whether elevated CRP levels occur prior to the biological onset of cancer or whether they serve as a risk factor for the onset of cancer." (PMID 38910781, 2024). "In multivariable Cox-regression models, both baseline CRP and longitudinal changes in CRP were significantly associated with a 17% and 8% increased risk of developing cancer respectively (HRCRP, 1.17; 95% CI, 1.09 to 1.26 and HRΔCRP, 1.08; 95% CI, 1.01 to 1.15)." (PMID 37019514, 2023). "DUET also promoted improvements in levels of CRP and glucose that have been observed in other more intensive weight loss interventions among cancer survivors, though few differences were detected in other biomarkers typically associated with weight loss, i.e., leptin, adiponectin, and insulin." (PMID 36900368, 2023). "CRP, synthesized by the hepatocytes in response to proinflammatory cytokines, has been linked to poor prognosis of various cancers including esophageal, bladder, melanoma, and other cancers." (PMID 38104105, 2023). "Hemoglobin, LDH, CRP, and albumin levels could be used as predictive factors for cancer patients with associated type two diabetes, highlighting the importance and impact of metabolic and inflammatory disorders encountered in these chronic diseases." (PMID 37627906, 2023). "CRP, a prototype acute phase protein synthesized in hepatocytes in response to inflammatory changes, has been widely reported to be associated with poorer prognosis in various types of cancer." (PMID 37015898, 2023). "Moreover, they reported that high CRP level and weight loss grade were independent factors negatively affecting the survival of patients with cancer." (PMID 37985353, 2023). "C-reactive protein (CRP) has been recognized for a long time as a marker of systemic inflammatory response, and comprehensive investigations have established its association with short survival rates in patients with various types of cancer." (PMID 36875097, 2023).
cancer (continued). "Recent evidences revealed that elevated serum CRP level was associated with several human cancers." (PMID 36793395, 2023). "ICU admission risk for cancer patients who presented to the ED with COVID-19 infection was significantly associated with chemotherapy within one month, a respiratory rate at triage above 22 breaths per minute, oxygen saturation less than 95%, and a higher CRP." (PMID 37643201, 2023). "In addition, increased CRP levels have been reported to be of value in predicting the outcome and prognosis of cancer-associated gallbladder resection." (PMID 37873776, 2023). "Namely, OS could lead to chronic inflammation, which could then mediate cancer development and extensive research has demonstrated an association with interleukin-6, C-reactive protein (CRP), and ferritin, with cancer." (PMID 37965473, 2023). "Among STEMI patients, higher C-reactive protein, higher platelet counts, and lower hemoglobin were associated with cancer incidence during the first year after STEMI (HRs 2.93 for C-reactive protein > 10 mg/dL, 2.10 for platelet count > 300*109, and 3.92 for hemoglobin < 7.5 mmol/L)." (PMID 36947265, 2023). "Thus, a higher CRP is considered to be a prognostic factor, with previous results showing associations with various types of cancers in patients." (PMID 37258608, 2023). "At the same time, the low concentration group (<0.08 mg/dL) was used as the control group, the higher CRP concentration group (>0.46 mg/dL) was associated with higher all-cause mortality (HR = 1.62, 95%CI = 1.34–1.96, P < 0.001) and cancer mortality (HR = 1.62, 95%CI = 1.15–2.28, P = 0.006)." (PMID 35571939, 2022). "Because inflammatory markers such as C-reactive protein have been associated with both cancer diagnoses and mortality, the association between higher handgrip strength and lower specific cancer mortality via reduction of such inflammatory marker seems plausible and deserves exhaustive investigation." (PMID 35639798, 2022). "Moreover, increased CRP levels were linked to lymphocytopenia and impaired T cell response in tumors, which can further promote cancer progression." (PMID 35619963, 2022). "At the same time, the low concentration group (<0.08 mg/dL) was used as the control group, the higher CRP concentration group (>0.49 mg/dL) was associated with higher all-cause mortality (HR 1.65, 95%CI 1.24–2.19, P = 0.001) and cancer mortality (HR = 3.25, 95%CI 1.82–5.80, P < 0.001)." (PMID 35571939, 2022). "CRP is often used as a sign of inflammation and inflammaging, and cohort studies have described associations between CRP levels and overall cardiovascular and cancer mortality." (PMID 35160156, 2022). "The relationship between CRP and cancer has been hypothesized to exist either through chronic inflammation, CRP playing a causal role or by the elevated levels reflecting an underlying malignant or premalignant state." (PMID 35494048, 2022). "In our previous study in Mexican Americans, we reported that study participants in the 4th quartile with the highest CRP levels had a significantly 1.88-fold increased risk of cancer (HR = 1.88, 95% CI: 1.12, 3.13) compared to those in the 1st quartile with the lowest CRP levels." (PMID 35804816, 2022). "Indeed, the magnitude of the increase in CRP concentrations has been shown to be associated with poorer survival in patients with cancer, particularly in patients with advanced disease." (PMID 35807934, 2022). "In addition, we reported that among all biomarkers of AL score, increased levels of triglyceride and CRP were associated with increased risk of cancer." (PMID 35804816, 2022). "Furthermore, no evidences of non-linear causal effects were observed between genetically predicted CRP concentration and risk of overall cancer or site-specific cancer." (PMID 36117174, 2022). "Previous studies showed that elevated D‐dimer, fibrinogen, and CRP could be potential biomarkers of cancer‐associated acute ischemic stroke." (PMID 36065806, 2022).
cancer (continued). "In addition, there was growing evidence that elevated CRP levels are associated with cancer disease risk." (PMID 35996695, 2022). "Furthermore, the levels of H3Cit-DNA complexes, MPO-DNA complexes and NE all correlated with CRP, indicating that NETs are associated with inflammation also in cancer patients." (PMID 35309730, 2022). "In conclusion, following the SARS-CoV-2 lockdown, an improved nutritional status in cancer patients at admission was observed with a decrease in the percentage of weight loss and CRP levels together with an increase in albumin levels compared to oncological patients admitted the previous year." (PMID 35807934, 2022). "After the adjustment of demographics, healthy behaviors, and SES factors, we found that higher levels of triglycerides and CRP were associated with 1.68 and 1.42 folds increased risk of overall cancer (triglycerides: HR = 1.68, 95% CI: 1.16, 2.43; CRP: HR = 1.42, 95% CI: 1.01, 2.01)." (PMID 35804816, 2022). "Unfortunately, we do not have data that allow us to answer precisely whether elevated CRP could be a causal link for VTE recurrence or could be an indicator of high-grade inflammation associated with cancer." (PMID 35681751, 2022). "High serum CRP levels are associated with colorectal cancer and other cancer types." (PMID 36010631, 2022). "Finally, six indicators of age, sex, cancer, CRP, T-SPOT, and ADA were included in the diagnostic scoring model by multivariate binary logistics regression, which showed that those six indicators significantly contributed significantly to the diagnosis." (PMID 36056429, 2022). "Many studies have demonstrated that CRP was associated with cancer survival." (PMID 35847918, 2022). "Pain assessed at baseline via the pain subscale of the European Organization for Research and Treatment of Cancer Quality of Life Questionnaire C-30 (EORTC QLQ-C30) was significantly associated with C-reactive protein (CRP), a hepatic secretory protein associated with systemic inflammation." (PMID 36072367, 2022). "Regarding the association between CRP and the prognosis of patients with cancer, CRP is the most common marker used to evaluate the magnitude of systemic inflammation because of its sensitivity, specificity, and reproducibility of analysis in hospital laboratories." (PMID 35690739, 2022). "Leptin, CRP, fasting insulin, and estradiol appear to mediate the effect of high BMI on cancer risk to different extents, with likely varying degrees of importance between cancers." (PMID 35048536, 2022). "Multivariate logistic regression analysis, as a stepwise descending method with the variables that were significant factors in the univariate analyses, demonstrated that 30-day mortality was associated with malignancy (p = 0.003), higher CRP (p = 0.007), and higher UA/Cr (p < 0.001)." (PMID 35054360, 2022). "CRP can induce a variety of inflammatory cytokines associated with cancers, such as interleukin-6." (PMID 35300627, 2022). "In addition, the causal relationship between CRP and cancer risk remained to be explored due to the potential unmeasured confounders or reverse causality in observational studies." (PMID 36117174, 2022). "The SARS-CoV-2 lockdown improved the nutritional status of cancer patients at admission, with a decrease in the percentage of weight loss and CRP concentrations together with an increase in albumin levels compared to oncological patients admitted the previous year in a single center." (PMID 35807934, 2022). "The C-reactive protein to albumin ratio (CAR) is associated with poor prognosis in various cancers." (PMID 36397047, 2022). "Our research result was that CRP was associated with all-cause mortality and cancer mortality." (PMID 35571939, 2022).